MID1 (midline 1)
Description:
Has E3 ubiquitin ligase activity towards IGBP1, promoting its monoubiquitination, which results in deprotection of the catalytic subunit of protein phosphatase PP2A, and its subsequent degradation by polyubiquitination.
Synonyms: FXY; RNF59; TRIM18; XPRF; OS; BBBG1; GBBB; GBBB1; MIDIN; OGS1; OSX; ZNFXY
Tractability: PROTAC: ubiquitination databases record sites on it.
Gene: Protein-coding gene on chromosome X (10,445,310 to 10,833,654, reverse strand). Ensembl gene ENSG00000101871.
Subcellular location: Cytoplasm; Cytoplasm, cytoskeleton; Cytoplasm, cytoskeleton, spindle
Subcellular location (Human Protein Atlas): Centriolar satellite; Cytosol; Golgi apparatus
Pathways (Reactome):
Immune System: Interferon gamma signaling
Gene Ontology:
Molecular function: enzyme binding; identical protein binding; microtubule binding; phosphoprotein binding; protein binding; protein homodimerization activity; ubiquitin protein ligase binding; ubiquitin protein ligase activity; zinc ion binding
Biological process: positive regulation of stress-activated MAPK cascade; protein localization to microtubule; microtubule cytoskeleton organization; pattern specification process; regulation of microtubule cytoskeleton organization; positive regulation of intracellular signal transduction
Cellular component: cytoplasmic microtubule; cytosol; microtubule; cytoplasm; microtubule associated complex; cytoskeleton; microtubule cytoskeleton; spindle
Gene-disease validity (ClinGen):
ClinGen rates the evidence that MID1 causes each of these diseases.
X-linked Opitz G/BBB syndrome (X-linked): Definitive.
Homologues: Orthologues: macaque MID1 (100% identical), guinea pig MID1 (99% identical), rat Mid1 (99% identical), pig MID1 (98% identical), chimpanzee MID1 (96% identical), mouse Mid1 (95% identical), tropical clawed frog mid1 (93% identical), zebrafish mid1 (80% identical), dog MID1 (76% identical). Paralogues in human: MID2 (76% identical), TRIM27 (20% identical), TRIM25 (19% identical), TRIM7 (19% identical), PML (18% identical), TRIM50 (18% identical), TRIM11 (18% identical), TRIM41 (18% identical), TRIM47 (18% identical), TRIM39 (17% identical), MEFV (17% identical), TRIM58 (17% identical), and 68 more.
Diseases named in the same sentence as MID1 in open-access papers:
MID1 is named in the same sentence as 97 diseases in open-access papers, as found by Europe PMC text mining. Sharing a sentence is not in itself a finding about the gene and the disease. The quoted sentences say what the papers report.
Opitz syndrome (32 papers, 2007 to 2026). "TRIM18/MID1 has been genetically linked to the Opitz BBB/G syndrome (OS), a monogenic disorder characterized by developmental defects that appear in the embryo’s midline and that include lip-palate–laryngotracheal clefts and an imperforate anus." (PMID 39205302, 2024). "Two single exon duplications were found in MID1 in three patients supporting links between MID1-rearrangements and X-linked Opitz G/BBB syndrome." (PMID 37010288, 2023). "Opitz syndrome (OS) is a genetic heterogenous disorder characterized by developmental defects in midline structures, with MID1 as the causative gene of X-linked OS." (PMID 36759768, 2023). "MID1 first aroused attention in 1997, when mutations in MID1 were discovered as the cause of Opitz-BBB/G syndrome (OS), which is characterized by malformations of the ventral midline." (PMID 34659371, 2021). "Based on the mutation identified in MID1, however, a diagnosis of Opitz G/BBB syndrome seems most likely for this patient." (PMID 32656166, 2020). "Mutations in MID1 are associated with the X-linked Opitz G/BBB syndrome, characterized by midline defects such as CL and CP, hypertelorism, and laryngo-trachea-esophageal (LTE) abnormalities." (PMID 31122291, 2019). "Mutations in MID1, which encodes a microtubule-binding protein, have been found in ~50% of Opitz GBBB syndrome patients consistent with the genetically heterogeneous nature of the disorder." (PMID 29311971, 2017). "Mutations in MID1 have been associated with the X-linked form of Opitz syndrome, which is characterized by midline abnormalities such as cleft lip, laryngeal cleft, heart defects, hypospadias, and ACC." (PMID 27087860, 2016). "For instance, mutated TRIM32 leads to limb-girdle muscular dystrophy type 2H; mutations in TRIM18 (MID1) cause Opitz G/BBB syndrome; and TRIM63/MuRF1 mutations result in hypertrophic cardiomyopathy." (PMID 25263070, 2014). "Mutations in the MID1 protein have been found in patients with Opitz BBB/G syndrome (OS), which is characterised by multiple malformations of the ventral midline." (PMID 18949047, 2008). "Mutations in the X-linked MID1 gene are responsible for Opitz G/BBB syndrome, a malformation disorder of developing midline structures." (PMID 18005432, 2007). "•Opitz-syndrome-associated mutations in MID1 PRYSPRY domain mapped." (PMID 40821731, 2025). "MID1 gene mutation is associated with X-linked Opitz G/BBB syndrome." (PMID 34276780, 2021). "Mutations in the X-linked MID1 gene cause Opitz G/BBB syndrome (OS)." (PMID 18005432, 2007). "Of note, the MID1 protein, encoded by the gene responsible for the X-linked form of Opitz G/BBB syndrome, is also a microtubular protein and the two products might physically and/or functionally interact contributing to the development of the embryonic midline structures." (PMID 35205294, 2022). "Furthermore, mutations to the Mid1 gene have been identified in patients with X-linked Opitz G/BBB syndrome, an inherited multiple-organ disorder primarily affecting midline structures, although the pathological mechanisms remain unknown." (PMID 33953293, 2021). "However, MID1 is the gene responsible for the Xp22-linked form of Opitz syndrome (OMIM 145410)." (PMID 34777475, 2021). "There was a 6.4% (3/47) rate of copy number abnormality (Trisomy 21, MID1‐related Opitz G/BBB syndrome and a 2q11.1 duplication), all of which were anomalous, rendering a 13.6% (3/22) rate of CMA abnormality among non‐isolated FIUVV." (PMID 40964892, 2026). "MID1 gene was first cloned at the breakpoint at Xp22 in an Opitz syndrome patient carrying an X-chromosome inversion and was subsequently identified as the causative gene in patients with X-linked Opitz syndrome." (PMID 36759768, 2023). "TRIM18 is one member of TRIM family proteins and is encoded by Midline 1 gene on the X chromosome, whose mutations are linked to a rare genetic disease called X-linked Opitz G/BBB Syndrome (XLOS)." (PMID 35909127, 2022).
Opitz syndrome (continued). "Several genes were reported only in syndromic cases; CHD7 (CHARGE syndrome), CR1 (van der Woude syndrome), EFNB1 (craniofrontonasal syndrome), KISS1R (Kallmann syndrome), MID1 (Opitz G/BBB syndrome), REN (van der Woude syndrome), and SOX9 (Pierre-Robin syndrome)." (PMID 31122291, 2019). "Here, we report the molecular screening for mutations in the coding and splice site regions of the SPECC1L gene in samples of sporadic patients diagnosed with Opitz G/BBB syndrome who resulted negative for mutations in the MID1 gene responsible for the X-linked form of the disease." (PMID 35205294, 2022). "Moreover, loss of function of MID1 (like in Opitz syndrome) leads developmental problems, but causes no adult-life effects." (PMID 34659371, 2021). "CUL4B mutation may result in X-linked mental retardation; whereas TRIM family of E3 ubiquitin ligases have been implicated in several developmental disorders, e.g., TRIM50 in Williams–Beuren syndrome, Midline 1 (MID1) in Opitz syndrome, and TRIM37 in Mulibrey Nanism." (PMID 28579943, 2017).
X-linked Opitz G/BBB syndrome (15 papers, 2009 to 2025). X-linked form of Opitz G/BBB syndrome. "Mutations in MID1 gene cause X-linked Opitz Syndrome (OS), which is a congenital malformation characterized by craniofacial defects including cleft lip/palate (CLP)." (PMID 36759768, 2023). "In fact, TRIM18/MID1 is mutated in a developmental disorder characterized by midline defects, X-linked Opitz Syndrome (XLOS, OMIM 300000), and TRIM1/MID2 is responsible for another X-linked form of intellectual disability (MRX101, OMIM 300928)." (PMID 35053362, 2022). "In the X-linked Opitz syndrome, characterised by cerebellar midline defects, including vermis hypoplasia, the mutated gene, midline 1 (MID1), which encodes a ubiquitin ligase, lies genetically upstream of FGF17." (PMID 32298260, 2020). "Mutations in MID1 cause the X-linked Opitz GBBB syndrome (OSX, MIM 300000), a congenital midline malformation syndrome characterized by clefting of the lip/palate and a variety of other pathologies." (PMID 22723972, 2012). "In addition, we mapped the locations of missense mutations in MID1 associated with X-linked Opitz syndrome, suggesting that some of these mutations impair the conformational stability of the protein." (PMID 40821731, 2025).
prostate carcinoma (10 papers, 2014 to 2022). A carcinoma that arises from epithelial cells of the prostate gland. "With relevance to prostate cancer our previous investigations revealed an association of AR mRNA with the MID1 ribonuclear complex with AR mRNA via its trinucleotide repeat motifs and consequent upregulation of AR protein levels via this complex (unpublished results)." (PMID 24484909, 2014). "Very recently, we could also show that the anti-tumor effect of metformin in prostate cancer cells is in part caused by its disruptive effect on the MID1 protein complex and the subsequent downregulation of the AR protein." (PMID 24913494, 2014). "Together, these results indicated that silencing circMID1 inhibited the promotional effects of MDSC-Exo on prostate cancer growth via regulating signaling of miR-506-3p/MID1." (PMID 35918733, 2022). "Recently MID1 was found to up-regulate AR protein levels in several prostate cancer cell lines and its expression was negatively regulated by androgen signaling." (PMID 34276780, 2021). "Recent findings showed elevated MID1 expression in prostate cancer and alteration of the MID1/a4/PP2A axis in lung adenocarcinoma and MID1 expression levels positively correlate with tumour Gleason scores." (PMID 30941058, 2019). "The ubiquitin ligase MID1, which is over-expressed in prostate cancer tissue in a stage-dependent manner, enhances androgen receptor protein levels." (PMID 24913494, 2014). "Previous microarray data performed by our group showed MID1 to be negatively regulated by androgens in various AR positive prostate cancer cell lines (unpublished data)." (PMID 24913494, 2014). "Metformin disrupts the MID1 protein complex and reduces AR protein levels in prostate cancer cells identifying AR as an indirect metformin target." (PMID 24484909, 2014). "To further address the potential role of MID1 in prostate cancer, we evaluated MID1 and AR expression levels by immunohistochemistry (IHC) in prostate cancer specimens." (PMID 24913494, 2014). "Our IHC results with samples of prostate cancer tissues revealed that MID1 is mainly stromal in benign tissue areas." (PMID 24913494, 2014). "This scenario would suggest a role of disrupted MID1-AR equilibrium in the progression of prostate cancer to an androgen ablation therapy resistant stage." (PMID 24913494, 2014). "Taken together, our results suggest modified MID1 expression in prostate cancer along with high AR expression levels, reflecting one mechanism that contributes to prostate cancer progression." (PMID 24913494, 2014). "Furthermore, MID1 expression is increased in certain types of cancer for example in prostate cancer cells." (PMID 29293623, 2018). "Interestingly, in cancerous tissue the MID1 expression shifted to the epithelial compartment and was excessive in higher-grade tumors and metastatic lesions of prostate cancer." (PMID 24913494, 2014). "The same could be shown in another AR-positive prostate cancer cell line (LNCaP) and with other MID1-specific siRNAs." (PMID 24913494, 2014). "Thus MID1 represents a novel, multi-faceted player in PCa and a promising target to treat castration resistant prostate cancer." (PMID 24913494, 2014). "In the current study, we examined the role of MID1 in AR signaling and the potential mechanisms by which MID1 may contribute to prostate cancer initiation and/or progression." (PMID 24913494, 2014). "Besides, it was reported that MID1 could act as a translational inducer of AR protein, which in turn decreased MID1 levels in response to androgen stimulation in prostate cancer." (PMID 35004288, 2021). "The midline-1 (MID1) protein increased translation of the AR, and disruption of the MID1-α4/PP2A protein complex by metformin decreased AR protein levels and inhibited prostate cancer cell growth." (PMID 35327549, 2022). "Thus, the results showed that MDSC-Exo promoted prostate cancer cell migration, proliferation, and invasion through S100A9/circMID1/miR-506-3p/MID1 signaling." (PMID 35918733, 2022).
prostate carcinoma (continued). "Given the critical role of AR activation in prostate cancer initiation and progression, negative feedback regulation of MID1 by the AR may be an important and effective way in order to strictly control AR signaling." (PMID 24913494, 2014). "Taken together, the MID1 complex may be a promising therapeutic target in castration resistant prostate cancer, because in the absence of androgens it can modulate several major oncogenic players." (PMID 24913494, 2014).
Huntington disease (8 papers, 2016 to 2026). Huntington disease (HD) is a rare neurodegenerative disorder of the central nervous system characterized by unwanted choreatic movements, behavioral and psychiatric disturbances and dementia. "In the brain, MID1 binds to and induces translation of pathologically expanded CAG repeat mRNAs, which are the cause for neurodegenerative diseases such as Huntington’s disease and spinocerebellar ataxias." (PMID 29293623, 2018). "For example the MID1 protein binds to mutant huntingtin (HTT) RNA, which is linked to Huntington's disease (HD), at its CAG repeat region and induces protein synthesis of mutant protein." (PMID 27774050, 2016). "While MID1 has been implicated in RNA regulation of key molecules in Alzheimer’s and Huntington’s disease, it has not previously been implicated in TDP-43-driven neurodegeneration." (PMID 30357366, 2019). "Whereas the four MID1-targeting miRNAs that we have identified have not been linked to Huntington’s disease so far, all of them have previously been linked to carcinogenesis." (PMID 29293623, 2018). "Furthermore, TRIM18/MID1 is found to be associated with a regulatory complex involved in the translation of expanded CAG repeats, which are a shared feature of different neurodegenerative disorders, such as Huntington’s disease." (PMID 39205302, 2024). "MID1 enhances the translation of mutant CAG repeat mRNAs and is therefore contributing to the neuropathology of polyglutamine diseases such as Huntington’s disease." (PMID 29293623, 2018).
viral infection (8 papers, 2022 to 2025). "Notably, we observed that NSP9 interacted with MID1 but that this interaction was diminished following virus infection." (PMID 37854611, 2023). "Next, we confirmed that MID1 affects NSP9 function during virus infection." (PMID 37854611, 2023). "However, virus infection reduced the interaction between NSP9 and MID1, effectively inhibiting K48-linked ubiquitination and degradation of NSP9." (PMID 37854611, 2023). "Moreover, the E3 ubiquitin ligase Midline 1 (MID1) facilitated the K48-linked ubiquitination and degradation of NSP9, whereas virus infection inhibited the interaction between MID1 and NSP9, thereby inhibiting NSP9 degradation." (PMID 37854611, 2023). "However, the role of MID1 in viral infection has been reported infrequently." (PMID 37854611, 2023). "Expression changes in UPS genes identified in both ST_EPN_RELA and PF_EPN_B included several differentially expressed UPS genes associated with interferon gamma signaling (MID1, PIAS1, TRIM2, TRIM22, TRIM45) that may promote a proinflammatory milieu similar to that observed upon viral infections." (PMID 36293188, 2022). "However, virus infection reduced the interaction between NSP9 and MID1, which could not degrade NSP9 but promoted its expression." (PMID 37854611, 2023).
hypospadias (6 papers, 2014 to 2023). Hypospadias is the displacement of the urethral meatus on the ventrum of the penis. "It was also noted that 11 mutations in SRD5A2 gene, 6 mutations in AR gene, and one variant in MID1 gene in this study were also correlated to abnormal male genital development and hypospadias." (PMID 34276780, 2021). "Variants in the MID1 gene are associated with the X-linked recessive Opitz G/BBB syndrome (OMIM #300000), in which ARM, cardiac anomalies, TEF, hypospadias, hypertelorism and syndactyly are described." (PMID 32656166, 2020). "In this context it should be mentioned that such a bifurcated inhibition of androgen signalling by disruption of MID1’s function might also underly the phenotypical similarities Opitz patients share with patients suffering from partial androgen insensitivity syndrome, namely hypospadias." (PMID 24913494, 2014). "Hypospadias of all grades was found more commonly in males with MID1 mutations than in those without." (PMID 34276780, 2021).
viral myocarditis (6 papers, 2022 to 2025). Myocarditis that is caused by an infection with a viral agent. "Moreover, deletion of Mid1 decreased susceptibility of mice to viral myocarditis, pneumonia, and herpes simplex encephalitis by enhancing the production of type I IFN through its interaction with protein phosphatase 1A (PPM1A) responsible for dephosphorylation of TANK binding kinase 1 (TBK1)." (PMID 40443734, 2025).
Alzheimer disease (5 papers, 2011 to 2021). A progressive, neurodegenerative disease characterized by loss of function and death of nerve cells in several areas of the brain leading to loss of cognitive function such as memory and language. "It has been proposed that overexpression of mid1 leads to disturbance in microtubule-homeostasis, comparable to the tau-aggregation induced neuronal loss in Alzheimer's disease." (PMID 21699683, 2011). "Our data showing that miR-19b-3p targets MID1 provide one possible explanation for increased expression of MID1 in Alzheimer’s disease tissue, that may be caused by reduced levels of miR-19b-3p." (PMID 29293623, 2018). "We show here that miR-19b-3p targets MID1, a protein that we have previously shown to induce protein expression of two mRNAs that are crucial for the development of amyloid plaques in Alzheimer’s disease, namely BACE1 and APP." (PMID 29293623, 2018). "For example, MID1 binds to BACE1 mRNA and induces its translation linking translational regulation by MID1 to Alzheimer's Disease." (PMID 27774050, 2016). "Moreover, midline 1 (Mid1) has been reportedly expressed in the brains of patients with Alzheimer’s disease." (PMID 33419170, 2021). "Future studies should address if miRNA based therapeutics such as miRNA mimics of the four MID1-targeting miRNAs hsa-miR-19b-3p, hsa-miR-340-5p, hsa-miR-374a-5p and hsa-miR-542-3p could be used to downregulate MID1 in Alzheimer’s disease models and thereby counteract formation of amyloid plaques." (PMID 29293623, 2018). "Furthermore, we have observed increased expression of MID1 in Alzheimer’s disease brains." (PMID 29293623, 2018).
asthma (5 papers, 2021 to 2024). "It has been shown that allergic airway inflammation associated with rhinovirus infection leads to the upregulation of the E3 ubiquitin ligase midline 1 (MID1) in mouse bronchial epithelium, thus, the inhibition of MID1 attenuates rhinovirus-induced airway inflammation and asthma exacerbations." (PMID 35619695, 2022).